MUC17 (mucin 17, cell surface associated)
Diseases named in the same sentence as MUC17 in open-access papers (continued):
Sharing a sentence is not in itself a finding about the gene and the disease.
polyp (1 paper, 2017). A usually exophytic mass attached to the underlying tissue by a broad base or a thin stalk. "In both adjacent normal colon and polyp subtypes, cytoplasmic expression of MUC17 and Tn/STn-MUC1 was observed in crypt epithelial cells." (PMID 27705923, 2017). "Considering the high clinical utility of the appropriate polyp classification, in this study, we evaluated the potential of colonic mucins (MUC1, MUC4, MUC17, MUC2, MUC5AC, and MUC6) and associated glycans (Tn/STn-MUC1 and CA19-9) for differentiating SSA/P from HP and TA." (PMID 27705923, 2017).
renal cell carcinoma (1 paper, 2024). "Mucins such as MUC17 and MUC1 have been reported in relevant studies in renal cell carcinoma, although MUC1 was not identified as a survival-specific gene in our study." (PMID 38893126, 2024).
tubular adenoma (1 paper, 2017). A usually polypoid neoplasm arising from the glandular epithelium. "Expression of colonic mucins (MUC1, MUC4, MUC17, MUC2, and MUC5AC) and O-glycans [Sialyl LewisA (CA19-9) and Tn/Sialyl-Tn on MUC1] were analyzed in HP (n=33), SSA/P (n=39), and tubular adenoma (TA) (n=36) samples by immunohistochemistry." (PMID 27705923, 2017).
cancer (30 papers, 2011 to 2025). A tumor composed of atypical neoplastic, often pleomorphic cells that invade other tissues. "Accordingly, mutations in MUC16 (CA125) were selected for in EGFR-mut and KRAS-mut cancers while only mutations in MUC17 were selected in NEK." (PMID 36612014, 2022). "MUC17 also contributes significantly to maintaining cell homeostasis and modulating chronic inflammatory responses by activating signaling pathways associated with inflammation and cancer." (PMID 39980277, 2025). "Epigenetic regulation of mucin expression, such as MUC1, MUC2, MUC4, MUC5AC and MUC17, has been reported to be controlled by DNA methylation in a variety of cancer cells." (PMID 36778111, 2023). "We further explored the potential signaling pathways affected by the downregulation of MUC17 in drug-resistant cells, the activation of the NF-κB signaling pathway caused by gefitinib/osimertinib resistance may aggravate inflammation and the progression of malignant tumors." (PMID 36778111, 2023). "In accordance with this, it was shown that cells proliferating at a high rate, such as human cancer cells, have an increase in expression of muc-17." (PMID 37916189, 2023). "Six genes were found to be implicated in cancer etiology/progression/clinical outcomes with high degree of certainty: MMP1, DDX4, TRPM3, DPP6, KCNA1, and MUC17." (PMID 32625238, 2020). "This leads to increased expression of MUC17 in cancer cells, thereby inhibiting cancer cell proliferation and improving survival of patients with GC." (PMID 31262330, 2019). "Here, we provide the first report of the MUC17 regulatory mechanism under hypoxia, an essential feature of the tumor microenvironment and a driving force of cancer progression." (PMID 22970168, 2012). "Although little is known about the functional role of MUC17 in cancer, understanding the regulatory mechanism of MUC17 can be a key step in developing new strategies for cancer diagnosis and treatment." (PMID 22970168, 2012). "There are some implications for considering the functional role of MUC17 in cancer development." (PMID 22970168, 2012). "However, mutations in genes that are involved in immunoresistance of cancers such as ASXL, MUC4, MUC16 or MUC17 may negatively affect the efficacy." (PMID 36980598, 2023). "Thus, the combination of two agents demonstrates an enhanced effect of anti-cancer activity in which 5-Aza-induced upregulations MUC17 and MZF1 may promote the sensitivity of NSCLC resistant cells to EGFR-TKIs." (PMID 36778111, 2023). "For instance, MUC1, MUC5AC, MUC17, and CA19-9 are expressed in carcinomas originating from the conventional pathway, whereas carcinomas originating from serrated pathways do not express these mucins." (PMID 36980526, 2023). "For the 19 Mucin (MUC) family genes, nine of them were RMGs and four of them (MUC17, MUC5B, MUC4, and MUC16) were common RMGs shared in 8 to 17 cancer types." (PMID 30107644, 2018). "Therefore, we would like to focus our discussion on genes that have been reported in cancer research, such as ESRP2, MUC17, MYH10, and SSX2IP." (PMID 38893126, 2024). "For the three cancers, SNVs were more likely to be detected in the high-OGT expression group than in the low-OTG expression group, and the top five genes with the highest frequency of SNV were MUC17, PIK3CA, SI, SYNE1, and PTEN." (PMID 35356257, 2022). "However, MUC12, MUC15, MUC17, and MUC20 had a significant increase in methylation in only KIRP and KIRC, which goes against the overall observed demethylation of mucins in the cancers examined here." (PMID 28978023, 2017). "For MUC12, MUC17, MUC20 and MUC22, no statistical differences between cancer samples and normal controls were observed." (PMID 34828282, 2021).
tumor (23 papers, 2012 to 2025). "Malignant proliferation of tumor cells induced by gefitinib/osimertinib resistance were due to hypermethylation of the MUC17-specific promoter caused by the UHRF1/DNMT1 complex, which activates the NF-κB signaling pathway." (PMID 36778111, 2023). "MUC17 (mucin 17, cell surface associated) encodes a member of membrane-bound mucins, which are involved in tumor immunomodulation." (PMID 36203656, 2022). "In fact, both TTN and MUC17 have been directly or indirectly recognized as tumor-associated genes." (PMID 32731431, 2020). "For example, MUC17, MUC5B and MUC6 gene mutations in tumor region T4A of PtA predict the perturbation of O-glycan biosynthesis and processing, and the GO terms in T4A differ from GO terms in other tumor regions." (PMID 26619400, 2015). "In the present study, we provide the first evidence describing the regulatory mechanism of MUC17 in the hypoxic tumor microenvironment." (PMID 22970168, 2012). "MUC4, MUC16, and MUC17 were found in most tumor samples ( > 78%)." (PMID 38637560, 2024). "MUC17, one of the 21 mucin genes, also exhibits tumor suppressor properties." (PMID 37920164, 2023). "In addition, we found that the expression of MUC17 decreased gradually with the increase of tumor malignancy, but was not correlated with EGFR mutation status." (PMID 36778111, 2023). "Single nucleotide polymorphism (SNP) was responsible for such variants, and single nucleotide variants (SNVs) mostly occurred as C > A and C > T. However, the role of PCDH15, MUC17, RPIL1, DAMTS12, and PAPPA219 expressed in a tumor microenvironment remains to be studied." (PMID 36147496, 2022).
infection (5 papers, 2008 to 2024). The state of being infected such as from the introduction of a foreign agent such as serum, vaccine, antigenic substance or organism. "Given that Muc17 protected the small intestine against pathogenic infection, we reasoned that Muc17 deletion might also allow commensal bacteria to make direct contact with enterocytes and thereby disrupt epithelial homeostasis." (PMID 39699961, 2024). "In mice, intestine-specific deletion of the Muc17 gene was dispensable for colonic inflammation while rendering the small intestine abnormally sensitive to infection by the attaching effacing bacterium Citrobacter rodentium (C. rodentium)." (PMID 39699961, 2024). "Similarly, Muc17 levels in the cytoplasm of the crypt base also decreased in the mid and distal large intestine with infection and the apical expression in the surface epithelium also decreased." (PMID 19088856, 2008). "MUC17 silencing in Caco-2 and HT29-19A cells resulted in a profound reduction of occludin and ZO-1 levels and an increase in paracellular permeability after infection with enteroinvasive E. coli compared to WT cells." (PMID 38345099, 2024).
bacterial infection (2 papers, 2019 to 2024). "MUC17 has been suggested to play a role during bacterial infections, as suppression of endogenous MUC17 in human intestinal cell lines results in susceptibility to bacterial invasion." (PMID 31387973, 2019). "Accordingly, the relative risk of C. rodentium infection in Muc17ΔIEC mice peaked in Si5 mucosa and decreased toward the DC, suggesting that Muc17 primarily serves as a small intestinal defense mechanism during bacterial infection." (PMID 39699961, 2024).
MUC17 also shares sentences with these, for which no sentence is quoted: chronic gastritis (2 papers); Crohn disease (2); hyperplastic polyp (2); Infertility (2); Lung squamous cell carcinoma (2); osteosarcoma (2); adenocarcinoma (1); colorectal polyp (1); endometrial cancer (1); glioblastoma (1); ischemic colitis (1); metastatic cancer (1); mucinous colorectal adenocarcinoma (1); myelitis (1); optic neuritis (1); ovarian carcinoma (1); ovarian clear cell cancer (1); ovarian serous cystadenocarcinoma (1); rectal cancer (1); squamous cell carcinoma (1); thymoma (1).